NLRP3 (NLR family pyrin domain containing 3)
Diseases named in the same sentence as NLRP3 in open-access papers (continued):
Sharing a sentence is not in itself a finding about the gene and the disease.
Hypertension (158 papers, 2010 to 2026). The presence of chronic increased pressure in the systemic arterial system. "Hypertension has been increasingly linked to multiple inflammasomes, including NLRP3, AIM2, and NLRC4, contributing to vascular dysfunction and blood pressure regulation." (PMID 40433411, 2025). "Serum NLRP3 levels increase with age, which we identified as a risk factor for both periodontitis and hypertension." (PMID 40572711, 2025). "Together, these findings support a shared pathogenic mechanism across hypertension and PE, where NLRP3-driven inflammation and endothelial injury represent key therapeutic targets." (PMID 40867825, 2025). "The NLRP3 inflammasome acts as a pivotal signaling platform, contributing to endothelial damage and dysfunction in hypertension-associated conditions, including vascular smooth muscle remodeling and proliferation." (PMID 40227195, 2025). "The established cutoff value of 0.68 ng/mL demonstrated a relatively balanced sensitivity (62.3%) and specificity (63.0%), suggesting the potential of serum NLRP3 as a biomarker for identifying patients at risk of hypertension." (PMID 40572711, 2025). "The activity of the NLRP3 inflammasome is also associated with cell types implicated in pulmonary hypertension and systemic hypertension." (PMID 41194915, 2025). "This hypertension model is associated with inflammation in the kidney, and the NLRP3/IL1β/IL-18 signaling system is involved." (PMID 39576390, 2025). "Transgenic mouse models have demonstrated that the development of hypertension and its associated renal inflammation is at least partially dependent on the presence of functional NLRP3 inflammasomes." (PMID 39576390, 2025). "The development of hypertension and its associated kidney injury is partly dependent on the presence of functional NLRP3 inflammasome, which consists of NLRP3, transfer protein ASC (apoptosis-associated speck-like protein containing CARD), and Caspase-1." (PMID 39576390, 2025). "Endothelia dysfunction linked to NLRP3 inflammasome activation is central to metabolic syndrome and hypertension, driven by low-grade inflammation involving the innate and adaptive immune systems." (PMID 40227195, 2025). "NLRP3 inflammasome activation has been documented in placental tissues, immune cells, and kidneys of women with PE and is associated with hypertension, proteinuria, and endothelial injury." (PMID 40867825, 2025). "A 42-base variable number of tandem repeats (VNTR) polymorphism in NLRP3 has been linked to an increased susceptibility to essential hypertension." (PMID 40433411, 2025). "In conclusion, while current studies establish an association between NLRP3 inflammatory vesicles and hypertensive disorders, the specific mechanisms by which these vesicles regulate hypertension remain elusive." (PMID 38317229, 2024). "In the context of hypertension, it was found that a 14-day Ang II infusion caused elevated blood pressure with increased expression of NLRP3 in the aorta, as well as higher serum levels of IL-1β in mice." (PMID 39594530, 2024). "Patients with hypertension are characterized by high plasma levels of IL-1β and IL-18, the main end-products of NLRP3 inflammasome activation, which also associates with end-organ damage." (PMID 37123470, 2023). "NLRP3 is the primary inflammasome associated with hypertension and is activated by cathepsins and ER stress." (PMID 37292200, 2023). "In animal models of salt sensitive hypertension, absence, or inhibition of NLRP3 inflammasome has been found to prevent the development of hypertension and associated renal damage." (PMID 37123470, 2023). "Genetic mutations of the NLRP3 gene have been shown to be associated with the development of hypertension." (PMID 36620210, 2022). "ASC deficient mice and mice treated with MCC950, a novel NLRP3 inflammasome inhibitor, are protected from salt-induced renal inflammation, fibrosis and hypertension." (PMID 36620210, 2022).
Hypertension (continued). "This aroused the exploration of potential role of NLRP3 inflammasome in hypertension from diverse causes." (PMID 36204568, 2022). "NLRP3 inflammasome has also been implicated in the development of vascular dysfunction in hypertension." (PMID 36620210, 2022). "A variable number of tandem repeat polymorphism in CIAS1 gene that encodes NLRP3 has also been associated with increased risk of hypertension." (PMID 36620210, 2022). "A different polymorphism, in this case, an intronic 42 base pair variable number of tandem repeat (VNTR) in the CIAS1 gene encoding NLRP3, has also been linked to susceptibility to develop essential hypertension." (PMID 33494430, 2021). "The purpose of this study was to explore the association between the activation of NLRP3 inflammasome and hypertensive endothelial damage, and to demonstrate the protective effect of sinapine thiocyanate (ST) on endothelia in hypertension." (PMID 33633569, 2020). "Recent studies using a variety of animal models have shown that the development of hypertension and associated renal inflammation is dependent on the presence of functional NLRP3 inflammasome signaling." (PMID 32858955, 2020). "Subcutaneous infusion of Ang II caused more serious hypertension, vascular remodeling, oxidative stress, NLRP3 inflammasome activation, AMPK phosphorylation inhibition, and SIRT1 downregulation in the aorta of FNDC5−/− mice than those of WT mice." (PMID 32509148, 2020). "In salt-induced pre-hypertensive rats, NLRP3 inflammasome activation is associated with hypertension in the PVN." (PMID 32242284, 2020). "Noncoding mutations in NLRP3 were reported to be linked to hypertension susceptibility, and the expression of IL-1β was elevated in patients with essential hypertension." (PMID 31694192, 2019). "The association of NLRP3 genetic variant rs7512998 with blood pressure and hypertension was studied in a 50-year-old Finnish cohort with a subpopulation who had available data on blood pressure measurements also at the age of 45 years." (PMID 26523150, 2015). "It is to be noted that the NLRP3 gene polymorphism was an independent predictor of both systolic and diastolic blood pressure independently of prior diagnosed hypertension, sex and BMI by multivariate analysis." (PMID 26523150, 2015). "Pro-inflammatory factors such as NLRP3 and IL-1β, which are linked to local inflammation in periodontitis, may stimulate systemic inflammation and contribute to the development of hypertension." (PMID 40572711, 2025). "Moreover, polymorphisms in the NLRP3 gene have been associated with higher blood pressure and an increased risk of hypertension." (PMID 40867825, 2025). "Addressing other risk factors, such as hyperlipidemia and hypertension, may further contribute to mitigating NLRP3 activation." (PMID 40017533, 2025). "Additionally, noncoding RNAs, such as miR-1929-3 p, can inhibit NLRP3 activation in macrophages, thereby improving cardiac remodeling associated with hypertension." (PMID 41194915, 2025). "The NLRP3 complex, once activated, is responsible for processing and secreting pro-inflammatory cytokines, leading to pyroptotic cell death and abnormal activity associated with inflammation, which ends with hypertension and multiple diseases." (PMID 38791545, 2024). "NLRP3 inflammasome activities have been implicated in various cell types associated with pulmonary hypertension, including pulmonary arterial smooth muscle cells, pulmonary artery endothelial cells, and systemic hypertension." (PMID 38681198, 2024). "In our study, mice on a low Mg2+ diet exhibited elevated systolic blood pressure and increased NLRP3 inflammasome activation in kidney dendritic cells, which may contribute to intrarenal inflammation associated with magnesium deficiency-induced hypertension." (PMID 37293263, 2023).
Hypertension (continued). "Hyperhomocysteinemia, a risk factor for the development of hypertension and its complications, has been shown to induce NLRP3 inflammasome assembly, caspase-1 activation and pyroptosis in endothelial cells, while mice deficient in caspase-1 or NLRP3 are protected." (PMID 36620210, 2022). "Additionally, NLRP3 single nucleotide polymorphism variant rs10754558 (C>G) plays an important role in the severity of COVID-19 in elderly males with hypertension." (PMID 36620210, 2022). "Studies have found that the activation of the NLRP3 inflammasome can aggravate the vascular endothelial dysfunction, and ST can ameliorate the endothelial injury caused by hypertension by inhibiting the activation of the NLRP3 inflammasome, with a satisfactory antihypertensive effect." (PMID 33633569, 2020). "Although studies have emphasized the importance of the NLRP3 inflammasome in hypertension, the exact mechanisms underlying NLRP3 inflammasome and its involvement in aortic remodeling in essential hypertension remain unknown." (PMID 30906225, 2019). "In addition, macrophage polarization and the NLRP3 inflammasome are associated with hypertension." (PMID 38715976, 2024). "Finally, our study suggests clinical implications of inhibiting the WNK1 pathway, including the use of diuretics to treat high blood pressure, as inflammatory complications linked to NLRP3 regulation by the WNK1 pathway may arise." (PMID 34315884, 2021). "Furthermore, the expression of NLRP3 inflammasome components is increased in brain areas that control blood pressure in spontaneously hypertensive rats and is linked to increased vascular damage and high blood pressure." (PMID 32009974, 2019). "This study found that H2S in the PVN improves spontaneous hypertension by inhibiting the PERK/TXNIP/NLRP3 pathway and reducing sympathetic activity." (PMID 41964264, 2026). "NLRP3 inflammasome activation also plays a role in renal inflammation and hypertension, and its inhibition has been shown to lower blood pressure and renal fibrosis." (PMID 41431547, 2025). "NLRP3 and its inflammasome work together to play significant roles in the onset and progression of hypertension." (PMID 40079000, 2025). "Serum NLRP3 levels demonstrated a predictive value for hypertension (AUC 0.693, 95% CI 0.590–0.796, and p = 0.001), with an established cutoff value of 0.68 ng/mL (sensitivity 0.623, specificity 0.630)." (PMID 40572711, 2025). "These properties of NLRP3 and IL-1β highlight the growing interest in their study to elucidate the link between periodontitis and hypertension, as well as their potential as preclinical biomarkers for the risk of developing both conditions." (PMID 40572711, 2025). "EMD638683, a selective inhibitor that inhibits the activation of the NLRP3 inflammasome, was used to reduce cardiac fibrosis in a model of hypertension induced by Ang II in mice." (PMID 40079000, 2025). "In animal models, pharmacological inhibition of NLRP3, as well as genetic deletion of its components, has been shown to prevent the development of experimental hypertension, further supporting its role in blood pressure regulation." (PMID 40867825, 2025). "Emerging evidence highlights ED induced by NLRP3 inflammasome activation as a critical factor in hypertension development." (PMID 40227195, 2025). "Previous experimental studies have demonstrated the NLRP3 inflammasome’s involvement in the development of hypertension and hypertension-induced organ damage, whereas it has been associated with blood pressure reduction and renal protection in hypertension." (PMID 40572711, 2025). "Significant correlations were found between serum NLRP3 levels and the presence of hypertension (p = 0.001) and between saliva IL-1β levels and the presence of hypertension (p = 0.010)." (PMID 40572711, 2025).
Hypertension (continued). "Of the four pro-inflammatory markers, only serum NLRP3 showed prognostic value for arterial hypertension (AUC 0.693, 95% CI 0.590–0.796, p = 0.001), with an established cutoff value of 0.68 ng/mL and above (sensitivity 0.623, specificity 0.630)." (PMID 40572711, 2025). "Salt-sensitive hypertension (SSH) is the most severe form of hypertension, and the presence of NLRP3 inflammasome plays a crucial role in its pathogenesis." (PMID 39576390, 2025). "A 1 mmol/L increase in VLDL resulted in a 7-fold increase in the odds for hypertension (OR 7.035, 95% CI 1.223–40.477, p = 0.029), while a serum 1 ng/mL increase in NLRP3 increased the odds 1.6-fold (OR 1.616, 95% CI 1.161–2.248, p = 0.004)." (PMID 40572711, 2025). "In our study, we observed significantly different concentrations of NLRP3 in saliva and serum among the four clinical groups, with the highest levels found in patients with both periodontitis and hypertension." (PMID 40572711, 2025). "Recently, NLRP3 inflammasome has emerged as a promising therapeutic target for combating hypertension." (PMID 39576390, 2025). "Compared to other inflammasomes, the role of NLRP3 inflammasome in hypertension has been extensively studied." (PMID 40433411, 2025). "By activating the renin-angiotensin system and generating ROS in the paraventricular nucleus, direct inhibition of IL-1β, the primary proinflammatory cytokine in the NLRP3 inflammasome pathway, in addition to blocking NF-κB, also reduces hypertension." (PMID 40079000, 2025). "Elevated SUA reduces nitric oxide bioavailability via eNOS uncoupling, exacerbating hypertension, while simultaneously activating pro-inflammatory pathways (e.g., NLRP3/NF-κB) that weaken vascular integrity." (PMID 40743650, 2025). "In patients with hypertension, diabetes, and tobacco use, aortic NLRP3 expression is elevated and positively correlates with total cholesterol and low-density lipoprotein cholesterol, while negatively correlating with high-density lipoprotein cholesterol." (PMID 41194915, 2025). "The significance of the pro-inflammatory marker NLRP3 in the pathogenesis of hypertension can also be discussed based on our findings, showing higher serum levels in hypertensive patients than in normotensive individuals." (PMID 40572711, 2025). "Chronic inhibition of NF-κB activity in the PVN of salt-sensitive hypertensive rats delays the development of hypertension through reducing NLRP3 and IL-1β expression, as well as attenuating the activity of IKKβ and NAD(P)H oxidase." (PMID 40433411, 2025). "The use of serum NLRP3 to predict hypertension is based on the central role of inflammation in the pathogenesis of the disease." (PMID 40572711, 2025). "Among the pro-inflammatory markers studied, only serum NLRP3 showed prognostic value for arterial hypertension, with an area under the curve (AUC) of 0.693, indicating moderate accuracy in distinguishing hypertensive patients from normotensive individuals." (PMID 40572711, 2025). "Anti-NLRP3 therapy also benefits from reducing autoinflammation in the pathophysiology of hypertension." (PMID 40079000, 2025). "Pairwise comparisons showed significantly higher NLRP3 levels in both saliva and serum in the periodontitis and hypertension group than in the healthy group (p = 0.024 and p = 0.001, respectively)." (PMID 40572711, 2025). "In our multivariate binary logistic regression analysis, among all included variables, VLDL and serum NLRP3 emerged as statistically significant predictors of hypertension." (PMID 40572711, 2025). "This study also highlights the importance of inflammasome activation in hypertension, with concurrent involvement of the NLRP3/IL-1β and TLR4/NF-κB pathways in promoting kidney injury and inflammation." (PMID 40433411, 2025). "The NLRP3 inflammasome has been documented in both experimental and clinical hypertension, with higher circulating IL-1β B and caspase 1 levels leading to blood pressure elevation." (PMID 41431547, 2025).
Hypertension (continued). "The determination of a threshold value of 0.68 ng/mL for serum NLRP3 has prognostic relevance for the manifestation of arterial hypertension." (PMID 40572711, 2025). "Recently, a non-targeted metabolomics approach revealed nutritional intervention with β-OHB reversed the high salt-induced adverse effects including renal NLRP3-mediated inflammation, fibrosis, and hypertension." (PMID 38681198, 2024). "We were unable to assess the effects of NLRP3 inflammasome activation on hypertension and renal impairment in obese mice." (PMID 39604027, 2024). "This, in turn, triggers the activation of the NLRP3 inflammasome, fostering the proliferation of vascular smooth muscle cells and contributing to the initiation and progression of hypertension." (PMID 38590522, 2024). "NLRP3 inflammasome has been demonstrated to be involved in the pathogenesis of chronic cardiovascular diseases, including hypertension." (PMID 39052650, 2024). "According to recent research, individuals with hypertension consistently have elevated plasma levels of NLRP3." (PMID 38360728, 2024). "Another blood metabolite, β-hydroxybutyrate, a ketone body that serves as an energy source during starvation or exercise, shows several beneficial effects in the treatment of seizures, hypertension, NLRP3-mediated inflammation, and neurodegenerative diseases." (PMID 38352653, 2024). "Genetic or pharmacologic impairment of the NLRP3 inflammasome prevented blood pressure increases in mouse models of hypertension." (PMID 38665599, 2024). "Another example is pyrrolidine dithiocarbamate, a compound that inhibits NF-κB and can be infused into the hypothalamic paraventricular nucleus to block high salt by inhibiting the NLRP3 inflammasome and caspase-1, thereby inducing hypertension development." (PMID 38317229, 2024). "CMV infection can activate the NLRP3 inflammasome and promote the occurrence and development of hypertension." (PMID 38590522, 2024). "ROS sequestration inhibits NLRP3 inflammasome activation, attenuating hypertension-related inflammation." (PMID 38791545, 2024). "NLRP3 expression is reported to have a role in mediating inflammation and vascular function in PE as well as other hypertensive disorders." (PMID 38255935, 2024). "For instance, a recent study indicated that the HSD-activated NLRP3-dependent pathway promoted the process of hypertension." (PMID 37691056, 2023). "Downregulation of the NLRP3 inflammasome can delay the development of hypertension, and drugs that inhibit the NLRP3 inflammasome can lower blood pressure." (PMID 36873396, 2023). "Ang II-induced hypertension in mice can be attenuated by inhibition of NLRP3 inflammasome activation." (PMID 37226086, 2023). "This study represents the first study showing that dietary Mg2+ depletion activates the NLRP3 inflammasome and stimulates production of IsoLGs, both of which promote hypertension." (PMID 37293263, 2023). "Genetic or pharmacologic reduction of NLRP3 activity attenuates hypertension in numerous animal models of hypertension." (PMID 37293263, 2023). "NLRP3 mRNA was found to be increased in kidney tissue from patients with hypertensive nephrosclerosis, suggesting a role in the pathophysiology of human hypertension." (PMID 37293263, 2023). "Several lines of evidence suggest the importance of the NLRP3 inflammasome in the pathophysiology of hypertension." (PMID 37293263, 2023). "The first study investigating the correlation between NLRP3 and hypertension was in the exploration of relieving high blood pressure symptom in preeclampsia." (PMID 36204568, 2022). "The application of EMD638683, a selective inhibitor suppressing the activation of NLRP3 inflammasome, effectively reduced cardiac fibrosis in Ang II- induced hypertension mice model." (PMID 36204568, 2022). "NLRP3 inflammasome activation leads to nuclear factor-kappaB (NF-κB) signaling activation involved in the development and progression of hypertension." (PMID 35295586, 2022).